G6PD (glucose-6-phosphate dehydrogenase)
Diseases named in the same sentence as G6PD in open-access papers (continued):
Sharing a sentence is not in itself a finding about the gene and the disease.
Gilbert syndrome (4 papers, 2020 to 2026). An autosomal recessive inherited disorder characterized by unconjugated hyperbilirubinemia, resulting in harmless intermittent jaundice. "The HS phenotype may also be modified by co-occurrence with other disorders like glucose-6-phosphate dehydrogenase (G6PD) and Gilbert syndrome." (PMID 33014018, 2020).
head and neck squamous cell carcinoma (4 papers, 2022 to 2025). A squamous cell carcinoma that arises from any of the following anatomic sites: lip and oral cavity, nasal cavity, paranasal sinuses, pharynx, larynx, and salivary glands. "In this metabolic pathway, glucose-6-phosphate dehydrogenase (G6PD) and transketolase (TKT) are key downstream effectors driven by NRF2, contributing to the progression of head and neck squamous cell carcinoma." (PMID 38650924, 2024). "NRF2 up-regulates the pentose phosphate pathway (PPP) enzyme, glucose-6-phosphate dehydrogenase (G6PD) and transketase (TKT) mediated nucleotide biosynthesis, thereby promoting the malignant progression of head and neck squamous cell carcinoma (HNSCC)." (PMID 36203561, 2022). "Further evidence showed that PD inhibits glucose-6-phosphate dehydrogenase (G6PD), a rate-limiting enzyme in the pentose phosphate pathway, causing redox imbalance, which strongly affects cancer cell proliferation in vitro and in vivo in head and neck squamous cell carcinoma (HNSCC)." (PMID 39852136, 2024). "Glucose-6-phosphate dehydrogenase (G6PD) is a key regulator of NADPH production; overexpression of G6PD/TKT downstream of NRF2–MYC drives nucleotide biosynthesis and progression in head and neck squamous cell carcinoma (HNSCC)." (PMID 41470226, 2025).
ischemic heart disease (4 papers, 2016 to 2023). "The G6PD-deficient phenotype can protect against coronary heart disease by inhibiting 3-hydroxy-3-methylglutarylcoenzyme A reductase (HMG-CoA R) activity and reducing NADPH oxidase activity." (PMID 26944061, 2016). "In ischemic heart disease, G6PD is required to maintain cellular GSH levels and prevent ischemia–reperfusion-induced myocardial injury." (PMID 37938421, 2023). "Thus, O-GlcNA acylation of G6PD is promising as a new therapeutic target for ischemic heart disease." (PMID 37938421, 2023).
osteosarcoma (4 papers, 2015 to 2023). A usually aggressive malignant bone-forming mesenchymal neoplasm, predominantly affecting adolescents and young adults. "Studies have confirmed that LncRNA OR3A4 can regulate the growth of osteosarcoma cells by regulating miR-1207-5p/G6PD signaling, and inhibition of OR3A4 can increase the expression of miR-1207-5p, thereby inhibiting the level of G6PD in OS cells." (PMID 36387908, 2022). "We developed a new prognostic risk model for osteosarcoma based on 7 glycolytic genes (INSR, FAM162A, GLCE, ADH5, G6PD, SDC3, HS2ST1) by bioinformatics." (PMID 36387908, 2022). "In the present study, we analyzed the high-throughput RNA-sequencing data and clinical information of 86 osteosarcoma patients, and identified eight prognosis-related genes, including MAP3K5, G6PD, HMOX1, ATF4, ACADVL, MAPK1, MAPK10, and INS." (PMID 37285835, 2023). "A risk model based on seven glycolytic genes (INSR, FAM162A, GLCE, ADH5, G6PD, SDC3, HS2ST1) can effectively evaluate the prognosis of osteosarcoma, and in vitro experiments also confirmed the important role of INSR in promoting OS migration." (PMID 36387908, 2022). "The low level of G6PD inhibits the levels of NADPH and glucose in osteosarcoma cells." (PMID 36387908, 2022).
Parkinson disease (4 papers, 2019 to 2026). A progressive degenerative disorder of the central nervous system characterized by loss of dopamine producing neurons in the substantia nigra and the presence of Lewy bodies in the substantia nigra and locus coeruleus. "We investigated common and rare variants in the X-linked G6PD gene across six large cohorts of Parkinson disease patients and controls." (PMID 41376170, 2026).
pituitary tumor (4 papers, 2020 to 2023). A benign or malignant neoplasm affecting the pituitary gland. "For pituitary tumors, miR-1-3p was able to inhibit NADPH production and glycolytic processes in pituitary tumor cells by targeting G6PD, causing inhibition of proliferation and promotion of apoptosis." (PMID 37907984, 2023).
preeclampsia (4 papers, 2016 to 2022). Preeclampsia is a hypertensive disorder of pregnancy that is characterized by new-onset hypertension with proteinuria presenting after 20 weeks of gestation, and depending on mild or severe forms may initially present with severe headache, visual disturbances, and hyperreflexia. "Although some cases of preeclampsia have been linked to a mutation in the G6PD gene, it should be considered an acquired form of G6PD deficiency in most cases." (PMID 36431166, 2022). "Moreover, reduced G6PD activity was associated with impaired redox balance in fetal endothelial cells derived from preeclamptic pregnancies, providing further evidence that a prooxidant status is associated with preeclampsia, and that G6PD deficiency plays a major causative role." (PMID 34007401, 2021). "In preeclampsia, inactivation of glucose-6-phosphate dehydrogenase (G6PD), a rate-limiting enzyme in glucose metabolism, occurs in the fetal circulation, a phenomenon associated with the vascular dysfunction and oxidative stress observed in this disease." (PMID 27047385, 2016). "G6PD, another target of miR-423-5p involved in the pentose phosphate pathway (PPP) and glucose metabolisms, was also downregulated in a model of preeclampsia and gestational hypertension." (PMID 36614061, 2022).
syphilis (4 papers, 2019 to 2023). A contagious bacterial infection caused by the spirochete Treponema pallidum. "Interestingly, G6PD-normal vs. deficient blood donors were less likely to have screened positive for hepatitis C virus (p = 0.02) and rapid plasma reagin (indicative of syphilis, p = 0.03)." (PMID 30940186, 2019).
thyroid disorder (4 papers, 2018 to 2025). "The tests of thyroid function, erythrocyte sedimentation rate (ESR), C-reactive protein (CRP), CD64 index, T-lymphocyte subsets, and glucose-6-phosphate dehydrogenase (G6PD) were normal." (PMID 30342532, 2018).
Type 1 diabetes (4 papers, 2015 to 2022). "The deficiency of glucose-6-phosphate dehydrogenase (G6PD), another key enzyme of PPP, was reported to relate to higher PDR prevalence in type 1 diabetes." (PMID 35624805, 2022).
urinary tract infection (4 papers, 2017 to 2023). "Nitrofurantoin, a known precipitant of haemolysis in G6PD deficient patients (Youngsteret al., 2010), is recommended as first line treatment for urinary tract infections in pregnancy (Guptaet al., 2011), due to its safety, low cost, and efficacy." (PMID 29181452, 2017). "The evidence suggests a total daily dose of 200 mg nitrofurantoin may be used for short (3–5 day) course urinary tract infection treatment without G6PD screening when accompanied by appropriate advice." (PMID 35529053, 2022).
acne (3 papers, 2019 to 2023). An inflammatory process of the sebaceous glands which is characterized by comedones, nodules, papules and/or pustules on the skin. "A study with 56 Caucasian patients from the United States diagnosed with acne vulgaris and treated with topical dapsone evaluated the risk of hemolysis and/or hemolytic anemia in patients with G6PD enzyme deficiency." (PMID 34577605, 2021). "MDA and SOD levels were significantly escalated in acne patients,G6PD and CAT levels were significantly lower in acne patients." (PMID 34466486, 2019).
allergic rhinitis (3 papers, 2022 to 2024). Inflammation of the nasal mucous membranes caused by an IgE-mediated response to external allergens. "Among children, one patient suffered from Glucose-6-Phosphate Dehydrogenase deficiency, one patient suffered from allergic rhinitis, and the rest had no obvious comorbidities." (PMID 36076167, 2022).
Arrhythmia (3 papers, 2013 to 2026). Any cardiac rhythm other than the normal sinus rhythm. "Variants in 48 genes were examined, focusing on inherited arrhythmias, enzyme deficiencies (Glucose-6-Phosphate Dehydrogenase Deficiency [G6PDD], Porphyrias), Dravet Syndrome (DS) and Malignant Hyperthermia (MH)." (PMID 42278382, 2026). "Safety has always been a concern against the use of HCQ as it can cause life-threatening cardiac arrhythmias, QT prolongation, retinopathy causing loss of vision, hypoglycaemia, and haemolysis in G6PD-deficient patients." (PMID 36611040, 2023). "Hearts expressing both CryABR120G and RNAi targeted against Zw (the gene encoding G6PD) exhibited significantly shorter heart periods (increased heart rates), significantly reduced arrhythmia indices and systolic diameters, and significantly greater fractional shortening." (PMID 23818860, 2013).
autism (3 papers, 2021 to 2025). Persistent deficits in social interaction and communication and interaction as well as a markedly restricted repertoire of activity and interest as well as repetitive patterns of behavior. "Although G6PD enzyme deficiency is known for its role in hemolytic anemia, emerging studies have suggested a potential association between G6PD deficiency and neurodegenerative and neurodevelopmental disorders, including autism." (PMID 40868505, 2025).
breast tumor (3 papers, 2017 to 2023). "The aim of this study was to provide a better understanding of the role of PPP enzymes TKT and G6PD in breast tumors." (PMID 29290982, 2017). "In addition, analysis of the GEIPA database with a search of G6PD mRNA identified a similar level of G6PD mRNA between the normal and breast tumor tissues, which further affirmed our hypothesis." (PMID 38110365, 2023).
congenital heart disease (3 papers, 2022 to 2024). A heart disease that is present at birth. "Additional screening for CAH, G6PD, critical congenital heart disease and hearing is currently in the planning stage by the Directorate of Nutrition and Maternal and Child Health in the MOH." (PMID 38920845, 2024).
diabetic retinopathy (3 papers, 2020 to 2024). "In the retina, the G6PD deficiency can create stress conditions that can damage photoreceptor, retinal cells, and blood barrier function, leading to retinal diseases, such as photoreceptor degeneration and diabetic retinopathy." (PMID 32102234, 2020). "Based on the existing research, there are limited studies on the role and mechanisms of G6PD in diabetic retinopathy (DR)." (PMID 39621725, 2024). "This study aims to explore glucose-6-phosphate dehydrogenase (G6PD) activity in diabetic retinopathy (DR) and its correlation with inflammatory factors, elucidating the regulatory role of G6PD in DR pathology." (PMID 39621725, 2024). "Overall, treatments targeting G6PD have the potential to provide new approaches and strategies for the intervention of diabetic retinopathy (DR)." (PMID 39621725, 2024). "We hypothesize that targeting G6PD and enhancing its activity may have a beneficial effect on improving diabetic retinopathy." (PMID 39621725, 2024). "Therefore, this study aims to reveal the regulatory role of G6PD in diabetic retinopathy (DR) by analyzing G6PD expression changes in DR patients’ plasma and rats’ retinas." (PMID 39621725, 2024). "Therefore, the decrease in G6PD in diabetic retinopathy may directly damage retinal vascular endothelial cells." (PMID 39621725, 2024).
fibrosarcoma (3 papers, 2009 to 2017). A malignant mesenchymal fibroblastic neoplasm affecting the soft tissue and bone. "In nude mice, G6PD-overexpressing cells gave rise to rapidly growing, large fibrosarcomas, characterized by the abundance of new blood vessels, therefore suggesting angiogenic properties of high levels of G6PD." (PMID 28553614, 2017).
galactosemia (3 papers, 2021 to 2025). "In India, it is recommended to include screening programs for treatable disorders like CH, CAH, G6PD, galactosemia (GALT), biotinidase, CF, and hemoglobinopathy variations such as sickle cell disease in target populations." (PMID 38832201, 2024).
giardiasis (3 papers, 2022 to 2024). An infection of the small intestine caused by the flagellated protozoan giardia lamblia. "We found that compounds O2N-BZM7 and O2N-BZM9 have the most promising effects against giardiasis and trichomoniasis since they inactivate the G6PD::6PGL enzymes of both parasites, alter their structures, and efficiently cause the death of G. lamblia and T. vaginalis trophozoites." (PMID 36558035, 2022). "This work aimed to test an in-house chemical library of 120 compounds to identify active molecules that can alter G6PD::6PGL activity, which could be proposed as new, effective therapeutic agents to treat giardiasis." (PMID 36430836, 2022). "Here, we tested five synthesized benzimidazole derivatives as possible drugs for treating giardiasis and trichomoniasis, probing the bifunctional enzyme glucose 6-phosphate dehydrogenase::6-phosphogluconolactone from G. lamblia (GlG6PD::6PGL) and T. vaginalis (TvG6PD::6PGL) as a drug target." (PMID 36558035, 2022).
Hearing impairment (3 papers, 2018 to 2024). A decreased magnitude of the sensory perception of sound. "They determined that overexpression of G6PD is related to cochlear cellular degeneration because it increases NADPH synthesis, which helps maintain a balance between free radical production and cellular detoxification throughout aging, hence reducing the development of hearing loss." (PMID 38333758, 2024). "As a result of lack of a proper screening system for the G6PD enzyme, as well as the parents' lack of knowledge, the affected newborns are usually presented late to the hospital and have already developed higher jaundice complications, including hearing impairment." (PMID 30083525, 2018).
helminth infections (3 papers, 2011 to 2020). "In addition, we did not screen our volunteers for helminth infections or glucose-6-phosphate dehydrogenase deficiency (G6PD)." (PMID 21625634, 2011). "The inconsistencies observed in these human studies may be related to various limitations, including the lack of available immunological parameters, and no screen for helminth infections nor genetic deficiency such as glucose-6 phosphate dehydrogenase (G6PD) were undertaken." (PMID 33329563, 2020).
Hypoglycemia (3 papers, 2006 to 2020). A decreased concentration of glucose in the blood. "Chloroquine derivates can cause irreversible toxic retinopathy, cardiac rhythm disorders, gastrointestinal problems, hypoglycemia, bone marrow suppression and, in glucose-6 phosphate dehydrogenase (G6PD) deficient patients, severe hemolysis." (PMID 33312066, 2020).
hypothyroidism (3 papers, 2012 to 2024). Abnormally low levels of thyroid hormone. "Increase in activity of glucose-6-phosphate dehydrogenase (G6PD) due to neonatal hypothyroidism might be due to higher demand for NADPH as GR requires this reducing equivalence to generate reduced GSH from GSSG." (PMID 22315592, 2012).
lentivirus infection (3 papers, 2020 to 2023). Virus diseases caused by the Lentivirus genus. "Cell lines of Glucose-6-phosphate dehydrogenase(G6PD) knockdown in regorafenib-resistant cells or G6PD overexpression in HCC cell lines were stably established by lentivirus infection technique." (PMID 38111012, 2023). "We constructed cells stably expressing TSP50, G6PD and G6PD K171Q by lentivirus infection, and cell expressing these proteins was injected subcutaneously into nude mice." (PMID 33630390, 2021). "The regulatory function of NF-κB signaling pathway in G6PD transcription was analyzed by real-time RT-PCR, Western blot, luciferase and ChIP assay in ccRCC cells following treatment with NF-κB signaling activator/inhibitor or lentivirus infection." (PMID 33041664, 2020).
leprosy (3 papers, 2014 to 2022). Leprosy is a chronic infectious disease affecting primarily the skin and peripheral nervous system. "Haemolytic episodes in G6PD deficient subjects related to naphthalene intoxication, use of salicylates, transfusion of G6PDd blood into recipients with leprosy under sulpha drug therapy and excessive intake of rum or wine were reported in Curaçao." (PMID 24568147, 2014).
leptospirosis (3 papers, 2018 to 2025). A contagious bacterial infection caused by spirochetes of the genus Leptospira. "A hemolytic crisis following oxidative stresses in G6PD deficient patients can present mimicking leptospirosis." (PMID 29540210, 2018). "Hemolytic crisis following oxidative stresses in G6PD deficient patients can present mimicking leptospirosis." (PMID 29540210, 2018). "There are no past reports on hemolytic crisis in a G6PD deficient person presenting mimicking leptospirosis." (PMID 29540210, 2018).
lymphoma (3 papers, 2023 to 2025). A malignant (clonal) proliferation of B- lymphocytes or T- lymphocytes which involves the lymph nodes, bone marrow and/or extranodal sites. "Patients with stage IV group A lymphoma may show a decreased RBC count following disease progression; this manifestation might be confused with symptoms associated with G6PD enzyme deficiency." (PMID 39318598, 2024). "On one side, HL PBMCs displayed an increased H6PD activity, suggesting an acceleration of glucose-6P flux through the ER-PPP, as opposed to the response of its G6PD-dependent cytosolic counterpart that was shared by both lymphoma types." (PMID 37444643, 2023).
Merkel cell carcinoma (3 papers, 2020 to 2025). "Serum G6PD activity significantly increases with cancer stage in Merkel cell carcinoma and a notable decrease in G6PD activity has been observed following surgical resection or radiation therapy." (PMID 41374996, 2025). "Notably, in Merkel cell carcinoma, a rare neuroendocrine skin malignancy, serum G6PD activity increases significantly with cancer stage and has been established as a reliable prognostic biomarker." (PMID 41374996, 2025). "Notably, serum G6PD activity has been reported to increase with tumor stage and decrease after treatment in Merkel cell carcinoma, a type of skin cancer, which supports the broader clinical relevance of G6PD as a biomarker in oncology." (PMID 41514554, 2025).
metastatic disease (3 papers, 2022 to 2023). "Furthermore, the G6PD expression level was elevated in the advanced cancer stage or metastatic disease, which was associated with poor treatment outcomes." (PMID 36361665, 2022).
neuroblastoma (3 papers, 1976 to 2025). Neuroblastoma (NB) is the most common solid, extracranial childhood tumor. "This study demonstrated that inhibiting G6PD with 6-AN enhanced the cytotoxic effect of 5-ALA-mediated PDT against MYCN-amplified neuroblastoma cells, a subtype often resistant to the standard treatments." (PMID 41291487, 2025). "Furthermore, a recent study indicated that MSI2, a gene related to the malignant property of neuroblastoma cells, upregulated G6PD and enhanced PPP." (PMID 41291487, 2025). "We tested the effectiveness of combining 6-aminonicotinamide (6-AN), a glucose-6-phosphate dehydrogenase inhibitor that modulates nicotinamide adenine dinucleotide phosphate and glutathione redox balance, with PDT for treating neuroblastoma." (PMID 41291487, 2025). "Three bands of glucose 6-phosphate dehydrogenase were detectable in PGE1-treated cells, whereas the R020-1724-treated cells had two bands and the untreated neuroblastoma cells had only one band." (PMID 973999, 1976). "Although we did not evaluate G6PD gene expression in MYCN-amplified neuroblastoma cells, it was reported that MYCN levels were correlated with altered expression of proteins involved in enhanced glycolysis and increased oxidative phosphorylation." (PMID 41291487, 2025). "In this study, we hypothesized that combining G6PD inhibition with 5-ALA-mediated PDT would overwhelm GSH defenses and amplify the activity of ROS, resulting in the induction of enhanced cytotoxicity against MYCN-amplified neuroblastoma cells." (PMID 41291487, 2025).